ANXA8 (annexin A8)
Diseases named in the same sentence as ANXA8 in open-access papers (continued):
Sharing a sentence is not in itself a finding about the gene and the disease.
tumor (18 papers, 2007 to 2025). "Expression was consistently found upregulated in bladder tumors and derived cell lines and promoted tumor growth and metastases in vitro and in vivo, while ANXA8 silencing reduced tumor growth, migration, invasion and EMT." (PMID 36247003, 2022). "Among six pairs of tissues, the results of western blot showed that the expression of ANXA8 was notably higher in GC patients tumor tissues compared with the ANGTs." (PMID 32284751, 2020). "We have shown that ANXA8 has tumor-promoting functions in DGC." (PMID 40862051, 2025). "Additionally, in NSCLC, long non-coding MELTF Antisense RNA 1 has been shown to directly bind and displace the RNA-binding protein YBX1, which is involved in tumor development, thereby activating ANXA8 transcription and promoting tumorigenesis." (PMID 39716068, 2024). "Moreover, ANXA8 was found to be significantly overexpressed in Estrogen Receptor (ER)-negative versus ER-positive cases and significantly correlated with tumor stage, grade, and positive lymph nodes." (PMID 32823855, 2020). "Hence, we found an elevated expression of ANXA8 in tumor tissues with bioinformatics analyses, qRT-PCR, western blot and IHC." (PMID 32284751, 2020). "qRT-PCR in 58 pairs of fresh clinical samples verified the upregulation of ANXA8 in tumor tissues." (PMID 32284751, 2020). "Furthermore, we examined the expression of ANXA8 mRNA in primary tumor and adjacent normal mucosa tissues from OSCC patients by RT-LAMP." (PMID 26700817, 2016). "Analysis of tumor tissues showed significant downregulation of RBM15, KLF1, and ANXA8, along with reduced m6A content (p < 0.01), while TRIM13 expression was increased (p < 0.01) in the sh-RBM15 group compared to the sh-NC group." (PMID 39716068, 2024). "The expression of RSPO3, ALPP, VEGFC, ANXA8, HES2, GLP2R, and KRT14 in normal tissues was significantly higher than that in tumor tissues." (PMID 38240936, 2024). "The expression levels of ANXA2, ANXA3, ANXA4, ANXA8, and ANXA9 were significantly increased in tumor tissues compared with normal tissues." (PMID 34484309, 2021). "Annexin A8 (ANXA8) is down-regulated in LUAD and up-regulated in LUSC, according to our study has been classified as tumor suppressors in TSGDB, suggesting that a similar role in LUAD would benefit of further investigation." (PMID 31429720, 2019). "Annexin 8 (ANXA8), which is also down-regulated, has been shown to be transcriptionally down-regulated by epidermal growth factor (EGF), which correlates with the morphologic changes of EMT, along with tumour dedifferentiation." (PMID 33225905, 2020). "In tumor samples gene expression analysis showed no significant variation between WT and heterozygous KIT mutated tumors, with a high inner variability in ANXA8, FBN1, GALNTL4, MFAP5 and RABEP1 expression, which was partly reduced by separating exon 9 and exon 11 mutated tumors." (PMID 23593401, 2013).
gynaecological diseases (1 paper, 2024). "In gynaecological diseases, ANXA8 exhibits elevated mRNA expression in the porcine endometrium during days 11-13 of pregnancy, and ANXA8 stimulates the proliferation of porcine endometrial cells via the Akt signaling pathway." (PMID 39068672, 2024).
malignant carcinoma (1 paper, 2020). "Since then, a number of studies have focused on ANXA8 and have demonstrated that ANXA8 has shown to be tightly associated with various types of malignant carcinoma." (PMID 32284751, 2020).
ANXA8 also shares sentences with these, for which no sentence is quoted: benign tumor (2 papers); acute myelocytic leukemia (1); adenocarcinoma (1); age-related macular degeneration (1); asthma (1); atypical ductal hyperplasia (1); benign breast tumour (1); bipolar disorder (1); clear cell renal carcinoma (1); colorectal cancer (1); depression (1); Esotropia (1); gastric tumor (1); hepatocellular carcinoma (1); leukaemia (1); mesothelioma (1); mucinous cystadenocarcinoma (1); ovarian serous adenocarcinoma (1); ovarian tumor (1); pancreatic ductal adenocarcinoma (1); papillary thyroid cancer (1); polycystic kidney (1); psychiatric disorder (1); renal cell carcinoma (1); schizophrenia (1); squamous cell carcinoma (1); Stroke (1); thyroid cancer (1).